STAT3 (signal transducer and activator of transcription 3)
Diseases named in the same sentence as STAT3 in open-access papers (continued):
Sharing a sentence is not in itself a finding about the gene and the disease.
lupus (66 papers, 2012 to 2026). "STAT3 has been implicated in gamma herpes virus latency establishment in B cells, plasma cell differentiation and IgG1-switching in a murine model of lupus pathogenesis." (PMID 30619193, 2018). "For example, a B-cell-restricted SE, which was in contact with the SNP locus associated with systemic lupus erythematosus (SLE) and was mediated by STAT3, was associated with B-cell deregulation in SLE." (PMID 37194711, 2023). "First, in 2021, the lupus-like autoimmune phenotype was described in a cohort of ten STAT3 DN patients." (PMID 37140667, 2023). "In a lupus murine model, STAT3 knockout mice had a markedly reduced renal inflammatory infiltrate, as well as less pronounced renal IgG and C3 deposition, compared to controls." (PMID 35747794, 2022). "In skin lesions, higher mRNA levels of AIM2 and TFH‐related genes, including BCL6, IL21 and STAT3, were found in lupus patients than in NCs." (PMID 35343082, 2022). "The canonical pathways that were inhibited/decreased included the ICOS-ICOSL Signaling in T helper cells, and TGF-β Signaling, PKCβ Signaling in T lymphocytes, Systemic Lupus Erythematosus In T Cell Signaling Pathway, and STAT3 Pathway." (PMID 36032117, 2022). "STAT3 inhibitors have demonstrated preclinical efficacy in an animal model of osteoarthritis, lupus, and other inflammatory diseases." (PMID 34206429, 2021). "There were also higher intensities of pSTAT3/β-actin and STAT3/β-actin in lupus with a positive correlation of these intensities with IL-17 levels." (PMID 33271810, 2020). "T cell-specific silencing of STAT3 in lupus-prone mice resulted in amelioration of lupus nephritis, probably due to impairment of T cell stimulation of B cells to produce dsDNA autoantibodies." (PMID 33271810, 2020). "First, there was dysregulation of the IL-17/STAT3 axis in lupus resulting in elevated IL-17 and higher numbers of Th17 cells." (PMID 33271810, 2020). "hsa-miR-410-3p appears to directly target STAT3, leading to a reduction of IL-10 in T cells of patients with systemic lupus erythematosus, and was also shown to be elevated in the plasma of these patients." (PMID 32849505, 2020). "In a preclinical study, Stattic, a small molecular STAT3 blocker, alleviated nephritis in lupus prone MRL/lpr mice." (PMID 30524430, 2018). "Fe3+ Hb preferentially increased the functional maturation of bone marrow-derived dendritic cells (BMDCs) from lupus-prone mice, effects abrogated upon the inhibition of Stat3." (PMID 28694810, 2017). "There has been growing evidence to indicate that RhoA mediates phosphorylation of STAT-3 and STAT-5 in several cell types via ROCK and that targeted RhoA-ROCK inhibition modulates STAT-3 phosphorylation to shift toward a pathologic Th17/Treg imbalance in patients with lupus." (PMID 38243295, 2024). "In addition, inflammatory pathways were also prominent, including IFN-γ response, IL-6/JAK/STAT3, systemic lupus erythematosus, TLR signaling, immunoglobulin-mediated phagocytosis, NK cell–mediated cytotoxicity, and allograft rejection." (PMID 38386415, 2024). "In addition, selective STAT3 inhibition has been shown to ameliorate LN both in terms of glomerulonephritis and tubulointerstitial inflammation in murine models of lupus." (PMID 37457579, 2023). "Thus, future studies should focus on examining the impact of tapinarof co‐treatment with a STAT3 inhibitor on Tfh cell differentiation in a lupus mouse model." (PMID 37382269, 2023). "Indeed, STAT3 knock-out lupus-prone mice develop milder renal disease with regard to immune component infiltration and deposits in the kidneys." (PMID 37457579, 2023). "In lupus, the role of STAT3 has been identified in the pathogenesis of lupus nephritis." (PMID 35747794, 2022).
lupus (continued). "In this study, signaling pathways involved in cell adhesion molecules cams(CAMs), cytokine-cytokine receptor interaction, intestinal immune network for IgA production, leishmanin infection and systemic lupus erythematosus were differentially enriched in the highly expressed phenotypes of Stat3." (PMID 36454780, 2022). "Since the lupus-susceptible MRL-MpJ strain is the closest genetically to MRL/lpr, future experiments should examine PRL’s anti-apoptotic function in this strain to assess the influence of Fas on the prolactin–STAT3 axis." (PMID 33557010, 2021). "Foxp3 (Cre) × Stat3 (fl/fl) mice with pristine-induced lupus revealed enhanced peritoneal inflammation caused by lack of Treg17 and increased the percentage of Th17." (PMID 33271810, 2020). "In sum, lupus TC mice show an expansion of TFH cells that precedes the production of autoantibodies, and that is associated with increased mTORC1 activity and Bcl2 expression, as well as decreased STAT3 activation." (PMID 30348969, 2018). "To summarize, whether in lupus-prone or healthy mice, the fact that Hb acts via Stat3 to elicit inflammatory responses from, and phenotypic alterations on, dendritic cells is of interest." (PMID 28694810, 2017). "In addition, disregulation of the IFN-alpha/pSTAT3/IL-10 axis in systemic lupus erythematosus patients has revealed that the levels of type 1 IFN produced by plasmacytoid dendritic cells dictate the formation of regulatory B cells in a STAT3-dependent manner." (PMID 27486189, 2016). "Importantly, this study demonstrates the beneficial effects of cystamine on inducing antioxidant activities and CD4+/CD25+ regulatory T cells in lupus-prone mice by decreasing IL-6/STAT3 signalling." (PMID 23905628, 2013). "Mice with epidermal loss of JunB reportedly developed an SLE phenotype linked to increased epidermal IL-6 secretion, and facial skin biopsies of SLE patients displayed low levels of JunB protein expression, high IL-6, and activated STAT3 levels within lupus lesions." (PMID 22315615, 2012). "Experiments have confirmed that the STAT3 signaling pathway is involved in the progression of systemic lupus erythematosus (SLE)." (PMID 38542838, 2024). "Th17 cells significantly contribute to SLE pathogenesis, while inhibition of STAT3 delays the development of lupus pathogenesis by suppressing Th17 cell differentiation." (PMID 33632240, 2021). "Additionally, these investigators found that IFNα treatment polarized naïve B cell differentiation towards a lupus-like phenotype, which was reversed by a STAT3 inhibitor and was absent in STAT3-deficient donor naïve B cells." (PMID 33329603, 2020). "Moreover, STAT3 inhibition could represent a possible future therapeutic target in systemic lupus erythematosus." (PMID 32802115, 2020). "IL-10 is known to be elevated in the serum and tissues of patients with systemic lupus erythematosus (SLE) and the expression of IL-10 is activated by Stat3 (signal transducer and activator of transcription 3) in peripheral CD4+ T cells." (PMID 30816218, 2019). "STAT3 influences SLE T cell cytokine production, cell migration and B cell activity in lupus prone mice." (PMID 30524430, 2018). "Expression of p-STAT3 and STAT3 proteins was detected at higher levels in sorted CD19+CD5+CD1dhigh B cells from MRL/lpr mice than in sorted cells from B6 mice, and this finding suggests that activation of STAT3 may contribute to the expansion of B10 cells in lupus-prone MRL/lpr mice." (PMID 23638156, 2013). "Our gene expression analyses show induction of inflammatory pathways in tRCC, including IFN-γ response, IL-6/JAK/STAT3, TLR signaling, immunoglobulin-mediated phagocytosis, systemic lupus erythematosus, NK cell–mediated cytotoxicity, and allograft rejection." (PMID 38386415, 2024). "More specifically, lupus-prone mice treated with JAK2-STAT1 inhibitors, JAK1-STAT3 inhibitors, selective STAT3 inhibitors, and tofacitinib showed reduced serum levels of anti-dsDNA antibodies." (PMID 37457579, 2023).
lupus (continued). "Niclosamide exerted therapeutic effects on murine lupus models by suppressing TFH cells and plasma cells through STAT3 inhibition." (PMID 33632240, 2021). "STAT3 signaling inhibition resulted in decreased numbers of TFH cells in the spleen, which was correlated with an improvement in the lupus manifestation." (PMID 33632240, 2021). "An amount of 5 mg/kg ART significantly decreased the expression of p-Jak2/Jak2 and p-Stat3/Stat3 better than the 2.5 mg/kg treatment, suggesting that ART has therapeutic effects on lupus-prone MRL/lpr mice and involves Tfh cells and JAK–STAT signalling pathways." (PMID 35335880, 2022). "Considering the significance of STAT3 pathway in Tfh cell development and STAT3 as a key target of NCTD, we speculate that Tfh cells are also the target cells of NCTD treatment in lupus development." (PMID 34552214, 2022). "Our findings demonstrate that IL-22 binding to IL-22R in kidney epithelial cells activated the STAT3 signaling pathway, enhanced the chemokine secretion and then promoted macrophage infiltration to the kidney of MRL/lpr mice, thus aggravated LN in lupus-prone mice." (PMID 33717066, 2021). "We further explored a possible connection between interleukin-27 (IL-27), STAT3 signaling and IL-10 expression in CD4 T cells of mice with manifest lupus and found that IL-27 transcripts were increased in the spleens of ill NZB/W F1 mice compared to healthy animals." (PMID 33572870, 2021). "T cells of lupus patients showed poor response of STAT1, STAT3 and STAT5 to IFNα." (PMID 33271810, 2020). "In preclinical lupus models, including MRL/lpr and NZB/W F1 mice, JAK inhibition has yielded beneficial effects: JAK2–STAT1 blockade reduced glomerular immune complex deposits, proteinuria, and inflammatory infiltrates; JAK1/STAT3 inhibition decreased disease severity and autoantibody levels." (PMID 41194923, 2025). "There has been growing evidence to indicate that RhoA mediates phosphorylation of STAT-3 and STAT-5 in several cell types via ROCK, and that targeted RhoA-ROCK inhibition modulates STAT-3 phosphorylation to shift the pathologic Th17/Treg imbalance in patients with lupus." (PMID 37790522, 2023). "Based on these observations, it is reasonable to hypothesize that Ezh2 activity promotes lupus pathogenesis through non-canonical activation of the STAT3 pathway as well as through its methyltransferase activity." (PMID 32503684, 2020).
fibrosis (64 papers, 2011 to 2025). the formation of excess fibrous connective tissue in an organ or tissue in a reparative or reactive process. "This study contributes to the existing literature by identifying THBS1 and the JAK2/STAT3 pathway as promising molecular targets for therapeutic intervention in RILI-associated fibrosis, offering a feasible mechanistic basis for future antifibrotic strategies." (PMID 41394148, 2025). "Studies have revealed that ROS regulates cardiac fibrosis through multiple pathways, such as the Wnt/β-catenin, nuclear factor kappa-B (NF-κB), and signal transducer and activator of transcription 3 (STAT3) signaling cascades." (PMID 40448227, 2025). "We previously demonstrated that LCN2 promotes hepatic fibrosis in HFD-fed ob/ob mice by activating HSCs via LCN2/MMP9/STAT3-mediated signaling." (PMID 39832399, 2025). "Previous studies detected elevated STAT3 phosphorylation in all rodent models with liver injury and fibrosis and in the samples of patients with fibrosis and cirrhosis." (PMID 41163803, 2025). "For example, miR-21 represses sprouty RTK signaling antagonist 1 (SPRY1) and promotes cardiac fibrosis through the transcription factor signal transducer and activator of transcription 3 (STAT3) signaling pathway in rats." (PMID 38338950, 2024). "Single-cell analysis, histology, and qRT-PCR revealed that fibroblasts expressing high levels of fibrosis markers regulate STAT3 signaling in AT2 cells, which is accompanied by cystic organoid growth and MUC5B expression." (PMID 39578767, 2024). "SIRT3 overexpression alleviates cardiac fibrosis by deacetylating STAT3 and reducing the expression of NFATc2." (PMID 37196115, 2023). "STAT3 activation alleviates cardiac fibrosis via macrophage polarization regulation and STAT3 regulates mitochondrial function to mediate cardioprotection during ischemia-reperfusion injury." (PMID 35293279, 2022). "Diels, which can attenuate cardiac fibrosis by regulating the phosphatidylinositol 3-kinase (PI3K)/STAT3-mediated macrophage phenotype in aged rats after MI." (PMID 36225565, 2022). "Although we did not explore the mechanistic link between C188‐9 and TGF‐β, our data support the notion that STAT3 signaling is required for regulating cardiac fibrosis." (PMID 34056872, 2021). "It has been previously shown that miR-21 is negatively associated with SPRY1 in the pro-fibrotic pathway and enhanced cardiac fibrosis via CADM1/STAT3 pathway in a model of rat cardiac fibroblasts." (PMID 33804922, 2021). "Various genes which are potentially regulated by this miRNA are involved in calcium and potassium handling in myocytes (CACNB2, KCNN3), in protection of cells against oxidative stress (SIRT1), and in regulating cardiac fibrosis (STAT3)." (PMID 35052352, 2021). "Deletion of STAT5 in the hepatocyte induces liver fibrosis and hepatocarcinogenesis through promoting the activation of STAT3." (PMID 31511651, 2020). "Several signalling pathways have been analysed and targeted in cardiac fibrosis, senescence and ischaemia, on a dysmetabolic or cardiotoxic basis, including activation of the Stat3‐mediated pathway." (PMID 32940423, 2020). "P-JAK2, P-JNK, P-SRC, and P-c-ABL accumulate in fibroblasts in bleomycin- and TBRact-induced experimental fibrosis to a similar degree as in human SSc, confirming their suitability to study STAT3 signaling in SSc." (PMID 29066712, 2017). "Beyond the vasculature, resistin exerts direct detrimental effects on the myocardium by disrupting cardiomyocyte calcium handling and mitochondrial energetics, inducing pathological hypertrophy, and stimulating robust cardiac fibrosis via mechanisms involving JAK/STAT3 and TGF-β signaling." (PMID 41347124, 2025). "To ascertain whether PatA impacts HG-induced inflammatory fibrosis via the JAK2/STAT3 pathway, we performed Western blot analysis." (PMID 38794201, 2024). "Additionally, studies report IGFBP2, through the STAT3 pathway, induces lung fibrosis and inflammation in rats with severe pneumonia." (PMID 38918843, 2024).
fibrosis (continued). "Finally, we provided in vivo evidence that pharmacological inactivation of STAT3 inhibits profibrotic gene expression and subconjunctival fibrosis in a rat model of GFS." (PMID 37569586, 2023). "CADM1 expression is decreased in cardiac fibrosis tissue and fibroblast and may regulate STAT3 controlling cellular proliferation and, therefore, cardiac fibrosis development." (PMID 37894937, 2023). "In conclusion, STAT3 may play a dual role in hepatic fibrosis because of different upstream regulatory factors." (PMID 38074679, 2023). "In addition, rhein can protect the heart by reducing cardiac fibrosis, inhibiting the activation of STAT3 and P 38/MAPK signaling, and phosphorylation and nuclear enrichment of ERK, thereby reducing transcription of hypertrophic proteins." (PMID 36091816, 2022). "Given recent findings that TGF-β inhibition prevents cardiac fibrosis development, along with our findings that STAT3 inhibition reduces TGF-β-dependent fibrosis development, a more complete understanding of TGF-β signaling in CCC would uncover additional signaling contributors to cardiac pathology." (PMID 34504808, 2021). "Moreover, dapagliflozin attenuated cardiac fibrosis by regulating the macrophage polarization via STAT3 signaling in infarcted rat hearts." (PMID 30710997, 2019). "The protein expression and phosphorylation levels of STAT3 were not altered in livers of HCV-associated fibrosis and alcoholic cirrhosis patients, however, STAT3-DNA binding was markedly suppressed when compared to healthy livers." (PMID 28472150, 2017). "Additionally, studies suggest that STAT3 may contribute to hepatic fibrosis by interfering with the estrogen receptor signaling pathway." (PMID 38068980, 2023). "Thus, targeting STAT3 may be beneficial for different wound healing stages in subconjunctival fibrosis following GFS." (PMID 37569586, 2023). "We hypothesized that the PPARα-STAT3/SMAD pathway is critical to cardiac fibrosis in ACM mice." (PMID 36291052, 2022). "CCM111 prevents hepatic fibrosis via cooperative inhibition of TGF-β, Wnt and STAT3 signaling pathways." (PMID 39359922, 2024). "Meanwhile, the STAT3 and PI3K/Akt signaling pathways are two of the most classical downstream signaling pathways of β-AR that regulate cardiac fibrosis." (PMID 37630287, 2023). "Overall, these data indicate that ZB reduces ISO-induced cardiac fibrosis and inflammation by the BTK, STAT3, NF-κB, and PI3K/Akt signaling pathways in vivo." (PMID 37630287, 2023). "Fibrosis is the result of chronic inflammatory reactions, and FAT10 increases inflammation by increasing TNF-α/IFN-γ and NF-κB and STAT3 pathways, all of which were up regulated in fibrosis patients." (PMID 36386217, 2022). "Our studies further support miR-21 acts as important regulators in participate in cardiac fibrosis pathological, enhances cardiac fibrotic remodeling and fibroblast proliferation via CADM1/STAT3 pathway." (PMID 28335740, 2017). "In addition, miR-21 activates the STAT3 signaling by targeting tumor suppressor cell adhesion molecule 1 (CADM1) and enhances cardiac fibrosis." (PMID 38495094, 2024). "Some proteins of these genes have already been associated with pathophysiological processes in the kidney: in tubulointerstitial fibrosis (c-MYC, PTEN, STAT3, HIF-1α, PT53); podocyte injury (EGFR, PT53, CTNNB1, CREB1); epithelial-mesenchymal transition (PTEN); and glomerulosclerosis (DICER1, IL1β)." (PMID 37035314, 2023). "Furthermore, loganin can achieve cardioprotective effects through attenuating cardiac fibrosis, decreasing pro-inflammatory cytokine secretion, and suppressing the phosphorylation of critical proteins such as JAK2, STAT3, p65, and IκBα." (PMID 34194329, 2021). "One interesting finding showed that STAT3 expression and phosphorylation was not altered in HCV-fibrosis patients and alcoholic cirrhosis, while STAT3-DNA binding was markedly suppressed in all alcoholic and most HCV fibrosis patients when compared with that in normal healthy livers." (PMID 22136659, 2011).
fibrosis (continued). "Our hypothesis is that SBT-100 passes through all cells non-specifically and in adult mice and humans STAT3 is not actively produced in most tissues as found in the fibrosis literature (e.g., human skin and lung biopsies from healthy people reveal no STAT3)." (PMID 35886918, 2022). "Moreover, plumbagin may prevent hepatic fibrosis through inhibition of EGFR phosphorylation and STAT3 activation." (PMID 26550019, 2015).